STN1 (STN1 subunit of CST complex)
Description:
Component of the CST complex proposed to act as a specialized replication factor promoting DNA replication under conditions of replication stress or natural replication barriers such as the telomere duplex. The CST complex binds single-stranded DNA with high affinity in a sequence-independent manner, while isolated subunits bind DNA with low affinity by themselves. Initially the CST complex has been proposed to protect telomeres from DNA degradation. However, the CST complex has been shown to be involved in several aspects of telomere replication. The CST complex inhibits telomerase and is involved in telomere length homeostasis; it is proposed to bind to newly telomerase-synthesized 3' overhangs and to terminate telomerase action implicating the association with the ACD:POT1 complex thus interfering with its telomerase stimulation activity. The CST complex is also proposed to be involved in fill-in synthesis of the telomeric C-strand probably implicating recruitment and activation of DNA polymerase alpha. The CST complex facilitates recovery from many forms of exogenous DNA damage; seems to be involved in the re-initiation of DNA replication at repaired forks and/or dormant origins. Required for efficicient replication of the duplex region of the telomere. Promotes efficient replication of lagging-strand telomeres. Promotes general replication start following replication-fork stalling implicating new origin firing. May be in involved in C-strand fill-in during late S/G2 phase independent of its role in telomere duplex replication. Component of the CST complex, a complex that binds to single-stranded DNA and is required to protect telomeres from DNA degradation. The CST complex binds single-stranded DNA with high affinity in a sequence-independent manner, while isolated subunits bind DNA with low affinity by themselves. In addition to telomere protection, the CST complex has probably a more general role in DNA metabolism at non-telomeric sites.
Synonyms: OBFC1; FLJ22559; bA541N10.2; AAF-44; AAF44; CRMCC2; RPA-32
Tractability: Small molecule: a structure with a bound ligand is known. PROTAC: ubiquitination databases record sites on it.
Gene: Protein-coding gene on chromosome 10 (103,856,793 to 103,918,762, reverse strand). Ensembl gene ENSG00000107960.
Subcellular location: Nucleus; Chromosome, telomere
Subcellular location (Human Protein Atlas): Nucleoplasm
Pathways (Reactome):
Cell Cycle: Polymerase switching on the C-strand of the telomere; Telomere C-strand synthesis initiation
Gene Ontology:
Molecular function: protein binding; single-stranded telomeric DNA binding; telomeric DNA binding; single-stranded DNA binding; nucleic acid binding
Biological process: negative regulation of telomere maintenance via telomerase; telomere maintenance; telomere maintenance via telomere lengthening; positive regulation of DNA replication; telomere capping; DNA metabolic process; regulation of DNA metabolic process
Cellular component: chromosome, telomeric region; CST complex; nucleoplasm; nucleus
Genetic constraint (gnomAD): Loss-of-function variants: 20 observed, 29.8 expected, observed/expected ratio (o/e) 0.67, 90% interval 0.47 to 0.98. The upper end of that interval is the gene's LOEUF score, 0.98, which puts it in group 4 of 6, group 1 being the genes least tolerant of losing a copy. Missense variants: 277 observed, 338.23 expected, observed/expected ratio (o/e) 0.82, 90% interval 0.74 to 0.9. Synonymous variants: 109 observed, 126.02 expected, observed/expected ratio (o/e) 0.86, 90% interval 0.74 to 1.01.
Gene-disease validity (ClinGen):
ClinGen rates the evidence that STN1 causes each of these diseases.
cerebroretinal microangiopathy with calcifications and cysts 2 (autosomal recessive): Moderate.
Homologues: Orthologues: chimpanzee STN1 (99% identical), macaque STN1 (97% identical), pig STN1 (85% identical), rabbit STN1 (83% identical), dog STN1 (82% identical), guinea pig STN1 (79% identical), mouse Stn1 (71% identical), rat Stn1 (69% identical), tropical clawed frog stn1 (53% identical), zebrafish stn1 (42% identical). Paralogues in human: RPA2 (13% identical), RPA4 (11% identical).